CRP (C-reactive protein)
Diseases named in the same sentence as CRP in open-access papers (continued):
Sharing a sentence is not in itself a finding about the gene and the disease.
gastric cancer (continued). "Previous studies have found that some systemic immune response indexes, such as CRP, NLR, the Glasgow Prognosis Score (GPS), and PLR, can predict the clinical outcomes of gastric cancer patients." (PMID 33718137, 2021). "Previously, the platelet-to-lymphocyte ratio (PLR) and C-reactive protein (CRP), which are two inflammation-related biomarkers, were confirmed to be prognostic indicators in early gastric cancer, gastrointestinal cancers and CRC." (PMID 34001040, 2021). "The differences in CRP level and neutrophil counts between the two groups suggest that the application of ERAS reduced the inflammatory response in gastric cancer patients." (PMID 31116313, 2019). "In 104 patients with gastric cancer the serum proteins carcinoembryonic antigen (CEA), C-reactive protein (CRP), alpha 1-acid glycoprotein (AGP) (orosomucoid) and alpha 1-antichymotrypsin (ACT) were measured pre-operatively." (PMID 6896153, 1982). "Intraoperative CS administration mitigated postoperative CRP elevation but did not result in significantly improved survival in patients with cStage II–III gastric cancer." (PMID 40638018, 2025). "In addition to previous studies, we observed that the CRP/albumin and CEA/albumin ratios can be used to track the efficacy of treatment and predict the pathological response of patients experiencing gastric cancer." (PMID 38792528, 2024). "Unfortunately, routine testing for C-reactive protein (CRP) levels at the initial hospital admission of gastric cancer patients was not conducted." (PMID 38365617, 2024). "By analyzing postoperative indices such as CRP levels, Zhao believed that ERAS could effectively and safely inhibit the postoperative stress response in patients with gastric cancer." (PMID 38351544, 2024). "By contrast, another meta-analysis involving patients with gastric cancer, in which 8 out of the 9 included trials involved surgical patients, found no changes in CRP levels but a reduction in IL-6 levels." (PMID 35949598, 2022). "Moreover, a scoring system named Glasgow prognostic score based on inflammation (CRP and ALB) has been validated as versatile in predicting progress for gastric cancer." (PMID 33789664, 2021). "The relatively lower CRP level in the study group suggests that ERAS can relieve stress and inflammatory response in gastric cancer patients during the perioperative period and may thus reduce the risk of postoperative infection." (PMID 31116313, 2019). "Comparing patients with metastatic and nonmetastatic gastric cancer, it was found that they were different statistically according to prealbumin and CRP and not albumin." (PMID 26904109, 2016). "Here we tested correlation between serum GDF15 and CRP levels in our samples from gastritis patients and also tested correlation between serum GDF15 levels and histological differentiation grade in our samples from gastric cancer patients." (PMID 26892343, 2016). "In all patients with gastric cancer regardless of tumor stage, there was an increase in the concentration of C-reactive protein." (PMID 23554823, 2013). "On the other hand, the same study group could recently show, that CRP, but not albumin is an independent prognostic factor in gastric cancer patients." (PMID 29467943, 2018). "Interestingly, a latest literature indicated that modified Glasgow prognostic score (mGPS) is a robust predictor of gastric cancer survival as compared with NLR.8 mGPS is an inflammation-based score and is calculated on the basis of serum albumin and C-reactive protein (CRP) level." (PMID 27124056, 2016). "There was a statistical difference between those with metastatic (n = 43) and those with nonmetastatic (n = 28) gastric cancer according to levels of prealbumin and CRP; however they were not different regarding patient generated subjective global assessment (PG-SGA) and GPS." (PMID 26904109, 2016).
gastric cancer (continued). "During MNU treatment, the CRP level continually increased until the presence of intestinal metaplasia was elevated in the surviving animal that developed gastric cancer, confirming that CRP is not a specific gastric cancer biomarker." (PMID 21811552, 2011). "In conclusion, intraoperative administration of 5 mg/kg of CS mitigated postoperative CRP elevation; however, it did not provide a significant survival benefit after surgery for cStage II or III gastric cancer." (PMID 40638018, 2025). "We conducted a meta-analysis to determine the predictive value of the c-reactive protein (CRP), neutrophil-to-lymphocyte ratio (NLR), and Glasgow prognostic score (GPS)/modified Glasgow prognostic score (mGPS) in the clinical outcome of gastric cancer (GC) patients." (PMID 32716955, 2020). "We built a discriminant including CA724, CA242, TT, PLT, CRP, AST, and ascites for predicting patients with gastric cancer to be either stage IV or non-stage IV." (PMID 29967637, 2018).
pancreatitis (135 papers, 1994 to 2026). Inflammation of the pancreas. "High triglycerides have been implicated in inflammation, as evidenced by positive associations with C-reactive protein and pancreatitis risk." (PMID 38611646, 2024). "A rise of CRP levels can be caused by conditions other than infections, for example, trauma, malignancy, rheumatologic disorders, burns, pancreatitis, and periodic fever syndromes, and CRP values should be interpreted cautiously in these cases." (PMID 38254697, 2024). "Receiver operating characteristic (ROC) curves was used to evaluate the diagnostic performance of CRP/albumin ratio in determining the severity of pancreatitis." (PMID 36268355, 2022). "A negative strength of association was seen for history of weight loss (OR 0.51, CI 0.32–0.82), history of pancreatitis (OR 0.43, CI 0.24–0.73), low postoperative CRP (OR 0.50, CI 0.29–0.85), and increase in PDD (OR 0.58, CI 0.49–0.68)." (PMID 34370113, 2022). "In contrast, post-transplantation pancreatitis is known to cause an increase in CRP during the first few days after SPKT." (PMID 35743457, 2022). "On univariate analysis, a negative association was seen for history of weight loss, history of pancreatitis, low postoperative CRP, and increase in PDD." (PMID 34370113, 2022). "The fact that pancreatitis is an inflammatory condition is supported by increases in parameters associated with inflammation, such as C-reactive protein (CRP), Interleukin 6 (IL-6) and Tumor necrosis factor α (TNF-α), as well as histologic findings." (PMID 34256804, 2021). "In addition, in a predictive model study based on thrombus and inflammatory markers, PT, D-dimer, CRP, and PCT were associated with the severity of pancreatitis, only CRP was found to be significantly associated in our study." (PMID 38260093, 2023). "In multivariate analysis of patients over the age of 80 years, presence of moderate/severe pancreatitis, systemic and local complications, major polypharmacy, serum creatinine level (>2.4 mg/dL), and CRP level (>40 mg/dL) remained significantly associated with mortality." (PMID 36205509, 2022). "For example, in guideline, the supporting evidence for CRP is a diagnostic study, and the researchers use the Atlanta classification (2012) as a reference to determine the accuracy of CRP in the diagnosis of severe pancreatitis." (PMID 33419464, 2021). "Therefore, we performed broad and complicated analyses about peripheral lymphocyte subsets and pancreatitis-related diagnostic indicators (amylase, lipase, and CRP) in patients with AP of different severity and etiologies at different time points." (PMID 30881449, 2019). "It is unclear whether the baseline serum CRP concentration could predict or be correlated with hyperlipidemia and pancreatitis in MS dogs, to which they are prone, but an association between hypertriglyceridemia and pancreatitis is well documented in humans." (PMID 36290272, 2022). "Additionally, other events such as recent surgery, inflammatory insult, pancreatitis and trauma may cause fluctuations in CRP levels, respectively." (PMID 17868441, 2007). "A high predictive accuracy (95.2%) was observed in the study dataset, with elevated odds of severe pancreatitis associated with NLR (OR = 3.78, 95% CI: 2.83-5.06) and CRP (OR = 1.06, 95% CI: 1.05-1.08)." (PMID 42017091, 2026). "CONCLUSIONS: Based on our experimental results, CRP remains the most consistent APP for monitoring canine pancreatitis." (PMID 41807952, 2026). "C-reactive protein (CRP) is a well-established acute-phase reactant that tends to peak 48–72 h after the onset of pancreatitis and correlates with severity." (PMID 40299332, 2025). "Proglumide has a broad safety profile, and has been shown to decrease tissue inflammation, lower transaminases in hepatitis, and decrease pancreatitis as demonstrated by lowering serum lipase and C-reactive protein levels." (PMID 41008842, 2025).
pancreatitis (continued). "In severe pancreatitis cases (cPL ≥ 200 ng/mL, CRP ≥ 1.0 mg/L), the mean CPL level in the control group significantly (p < 0.05) increased from 920 ng/mL to 1,475 ng/mL." (PMID 40524736, 2025). "In severe pancreatitis cases, the mean CRP level in the control group significantly (p < 0.05) increased from 8.3 mg/L to 13.2 mg/L." (PMID 40524736, 2025). "CRP is the most effective biomarker for diagnosing mild pancreatitis, showing good specificity and some sensitivity." (PMID 40067493, 2025). "In summary, PCT is the preferred biomarker for diagnosing severe pancreatitis, while CRP provides some utility in mild cases." (PMID 40067493, 2025). "The index patient showed elevated WBC, CRP and serum lipase parameters during recurring pancreatitis episodes." (PMID 38582893, 2024). "During the consecutive progression of the first, third, fifth, seventh, and tenth days of hospital admission, the nCD64 index, PCT, and CRP indicators were detected in patients with severe pancreatitis." (PMID 38424643, 2024). "Arrival APACHE score, Ranson score (48th hour), BISAP score, and CRP level were statistically significantly higher in cases with severe pancreatitis." (PMID 36861872, 2023). "We identified six factors with a consistent and statistically significant association with ARDS, including SOFA score, APACHE II score, pulmonary sepsis, smoking, pancreatitis, and CRP." (PMID 37143620, 2023). "In the pancreatitis group, two dogs had increased serum C-Reactive Protein (79.47 mg/dL and 170.98 mg/dL, respectively; VetChroma; Boditech Med Inc., Republic of Korea) and cPL (>1,000 μg/L in both; Vcheck cPL; BioNote, Republic of Korea) concentrations." (PMID 37808100, 2023). "Dogs with pyometra and pancreatitis showed statistically significantly higher serum CRP and Hp and lower serum PON-1 and albumin concentrations when compared with healthy dogs." (PMID 37344860, 2023). "Optimum cut-off value of 4.35 was determined for CRP/albumin ratio via highest Youden index at which the sensitivity to predict severe pancreatitis was 87% as compared to 82% for CRP alone." (PMID 36268355, 2022). "In contrast, ePGD and other pancreatic IRI-associated complications, such as post-transplantation pancreatitis usually develop during the first few days after SPKT, being accountable for early increases in serum CRP levels." (PMID 35566689, 2022). "Other authors report CRP within RI in dogs with pancreatitis, possibly due to a longer, subclinical period before the presentation." (PMID 36290272, 2022). "Lastly, Delong's was applied for statistical comparisons between CRP/albumin ratio and CRP along as predictive marker of severity of pancreatitis." (PMID 36268355, 2022). "Secondary outcomes were days needed to lower triglycerides <10 mmol/L, highest CRP and percentage of patients with a severe course of pancreatitis." (PMID 35492338, 2022). "Serum amylase and CRP also decreased significantly, indicating that the severity of pancreatitis was reduced." (PMID 36327405, 2022). "Although, the statistical difference between CRP/albumin ratio and CRP levels alone isn't much, but overall, the sensitivity and accuracy are increased to predict severe pancreatitis by bringing albumin into the picture." (PMID 36268355, 2022). "The severity of pancreatitis was comparable in both groups; a severe course developed in 2 cases in both groups and the highest CRP was also comparable (229 vs. 211 mg/L, p = 0.69)." (PMID 35492338, 2022). "Secondary outcomes related to disease severity were also comparable: highest CRP 229 vs. 211 mg/L (p = 0.69) and severe course of pancreatitis in 2/11 cases in both groups (p = 1.0)." (PMID 35492338, 2022). "•CRP/albumin ratio >4.35 had a sensitivity of 87% and accuracy of 76% to predict acute severe pancreatitis." (PMID 36268355, 2022). "An elevated CRP level is one of the acute reactions of the body to infection and tissue damage, which is correlated positively with the severity of pancreatitis." (PMID 35345495, 2022).
pancreatitis (continued). "Vitamin D acts as a negative modulator of TNF-α and IL-6 release, decreasing TNF-α, IL-6, and C-reactive protein (CRP) levels in pancreatitis." (PMID 35631254, 2022). "Conversely, CRP is the most utilised biomarker for predicting disease severity in pancreatitis due to its low cost and widespread availability." (PMID 34720754, 2021). "Four guidelines recommend CRP as a reference indicator for the diagnosis of severe pancreatitis, of which 3 guidelines make clear recommendations, and the remaining guideline only mentions CRP in the content." (PMID 33419464, 2021). "A fourfold increase in ANGPTL4 levels was observed in the serum of pancreatitis patients, with increase in amylase, lipase, and CRP." (PMID 32638512, 2020). "In this study, we did a dynamic monitoring on peripheral lymphocyte subsets before and after a standard treatment; also, the indicators (CRP, amylase, and lipase) which highly correlate with pancreatitis were monitored throughout the study." (PMID 30881449, 2019). "The comparative analysis showed that after pancreatitis induction exosomes in plasma were enriched in a number of proteins presumably expressed by the liver (Apolipoproteins, C-reactive protein, Retinol binding protein, Alpha-2-macroglobulin...)." (PMID 31882721, 2019). "The purpose of our study is to assess the therapeutic consequences of contrast-enhanced computed tomography (CE-CT) and the predictive value of CRP for severe pancreatitis." (PMID 25214831, 2014). "Our goal is to assess the therapeutic consequences of contrast-enhanced computed tomography and the predictive value of CRP for severe pancreatitis in a retrospective analysis of clinical data." (PMID 25214831, 2014). "CRP levels have been reported more useful in monitoring disease activity than predicting the course of disease, mainly due to a 48 h delayed increase in CRP in patients that will develop severe pancreatitis." (PMID 23342125, 2013). "CRP was negatively correlated with IL-4 levels at 24 hours afterERCP in the patients with post-ERCP pancreatitis that supports the dominance ofinflammatory activity at this time after ERCP." (PMID 18670651, 2008). "Six additional patients outside of thisprospective study with post-ERCP-pancreatitis and daily CRP determinations were used to determinethe CRP-response curve in post-ERCP pancreatitis." (PMID 7533521, 1994). "Furthermore, low soluble CD73 activity at admission was a more accurate predictor than C-reactive protein (CRP) or creatinine change for the development of severe pancreatitis." (PMID 41601962, 2026). "Measuring CRP allows clinicians to evaluate whether the pancreatitis patient has developed peritonitis as a complication and determine the severity, and assess the clinical progression of the disease." (PMID 40524736, 2025). "In a retrospective study by Cardoso et al31 involving 379 patients, it was noted that the CRP value measured at 48 hours after hospital admission had good prognostic value regarding severe pancreatitis, pancreatic necrosis, and mortality, with a 48-hour CRP cut-off established at 170-190 mg/L." (PMID 40521831, 2025). "However, literature reports suggest that CRP, particularly when measured at 48 h (>150 mg/L), has high sensitivity and specificity for predicting severe pancreatitis." (PMID 40989798, 2025). "Future research directions could explore the feasibility of utilizing C-reactive protein as a marker for the severity of pancreatitis." (PMID 38318563, 2024). "For example, two C-reactive protein (CRP) measurements, taken several months apart, may both show normal values of <3 mg/L, while the patient could have developed and recovered from severe pancreatitis, with CRP of say, 280 mg/L in between." (PMID 39039248, 2024). "Measurement of the C-reactive protein (CRP) in serum, a clinical diagnostic marker of inflammation, showed no dramatic increase in caerulein induced pancreatitis." (PMID 37402858, 2023).